SOX10 (SRY-box transcription factor 10)
Diseases named in the same sentence as SOX10 in open-access papers (continued):
Sharing a sentence is not in itself a finding about the gene and the disease.
melanoma (continued). "The inhibition of SOX10 may be a potential effective way to treat melanoma." (PMID 33344444, 2020). "Finally, both SOX9 and SOX10 have roles in the etiology of melanoma." (PMID 33424631, 2020). "MITF and SOX10 co-occupy approximately 3,600 binding sites on chromatin in human melanoma cells, marking a subset of active regulatory elements that function to control key melanoma transcriptional programmes underpinning proliferation, invasion and metastasis." (PMID 31881017, 2019). "In this research, we aimed to resolve contradictory results whether SOX9 plays a positive or negative role in melanoma progression and determine whether SOX9 and its closely related member SOX10 share the same or distinct targets in mediating their functions in melanoma." (PMID 30642390, 2019). "SOX10 has been shown to be a crucial regulator in melanomagenesis but previous conflicting reports have not clearly defined whether SOX9 functions as a suppressor or an inducer in melanoma progression." (PMID 30642390, 2019). "In addition, NEDD9, SOX9, and SOX10 have been shown to be crucial for human melanoma metastasis." (PMID 30642390, 2019). "The distinct patterns of SOX9 and SOX10 expression in patient specimens probably reflect the heterogeneity of melanoma population harboring different genetic and epigenetic signatures since SOX9 expression could be regulated by DNA methylation and displays antagonistic relationship with SOX10." (PMID 30642390, 2019). "In addition, CXCR4 and SOX10 are critical melanoma-promoting genes." (PMID 31239444, 2019). "Therefore, we sought to evaluate SOX10 post-translational modifications in melanoma cells." (PMID 29315345, 2018). "In addition, a tumor marker (eg SOX-10) is included to define the melanoma cells in the tumor." (PMID 30042403, 2018). "Thus, the phosphorylation-dependent regulation of SOX10 transcription activity in melanoma cells may have implication in the development field as well." (PMID 29295999, 2018). "Therefore, understanding post-transcriptional regulation of SOX10 via phosphorylation may be crucial to developing effective anti-melanoma therapies." (PMID 29315345, 2018). "Interestingly, SOX10 was detected in fewer patients with thicker low-risk (T2A) melanomas or non-spread high-risk (stage II) MM." (PMID 27110718, 2016). "Furthermore, a rescue experiment indicates that SOX10 could reverse Fbxw7α-exerted migration inhibition in melanoma cells." (PMID 26461473, 2015). "Links between SOX10 and melanoma have also been identified and, as such, SOX10 might be an effective target for melanoma and for giant congenital nevi, which are benign melanocyte-containing skin lesions that can sometimes develop into melanoma." (PMID 25670789, 2015). "Likewise, Sox10 is required for the establishment of giant congenital naevi as well as melanoma." (PMID 25629959, 2015). "We next examined whether Fbxw7α regulated the endogenous SOX10 level in melanoma cells." (PMID 26461473, 2015). "Interestingly, the high level of SOX10 expression in melanoma cell lines is associated with lack of promoter methylation, except for the WM852 cell line." (PMID 25301735, 2014). "In contrast, SOX10 expression was significantly reduced or completely silenced in multiple digestive tumor cell lines of different histological origins including colorectal, gastric and esophageal cancers, but rarely silenced in melanoma cell lines which acts as a positive control." (PMID 25301735, 2014). "It was interesting that eleven of the molecules previously implicated in melanoma pathogenesis (described in the introduction) were identified as hubs in the Bayesian gene networks generated from our A375 cell dataset, including: BRAF, CCND1, RB1, PTEN, TYR, CDKN2A, and SOX10." (PMID 22536322, 2012). "In melanoma, ZEB1-driven phenotype switching mimics neural crest-like plasticity, while SOX10 re-expression drives dedifferentiation and therapy resistance." (PMID 41462674, 2025).
melanoma (continued). "SOX10, MITF, and other key factors in melanoma development are part of these motifs, impacting tumor progression and therapy resistance." (PMID 40458894, 2025). "Reactivation of neural crest-like transcriptional states has been observed in melanoma and other aggressive tumors, where factors such as MSH homeobox 1 (MSX1) and SRY-box transcription factor 10 (SOX10) drive dedifferentiation and enhance invasiveness." (PMID 41462674, 2025). "The regulatory landscape is further enriched by miRNAs that function as tumor suppressors by modulating SOX10, MITF, and their downstream effectors in melanoma." (PMID 40458894, 2025). "Classically, the immunohistochemistry reveals strong positivity for melanocytic markers, such as human melanoma black 45 (HMB-45), Melan A, S100 protein, and SOX10 (SRY (Y sex determination region) - Box 10)." (PMID 40978962, 2025). "When considering melanoma in the differential diagnosis of PUC, a panel of melanocytic markers, including S-100, Melan-A, HMB-45, and SOX10, is typically employed." (PMID 40893790, 2025). "SOX family members are common PAX protein co-factors; in melanocytes and melanoma, PAX3 interacts with SOX10 and drives a number of downstream genes, such as MITF, MET, and RET." (PMID 40428399, 2025). "In melanoma, CD271 and SOX10 identify highly plastic, therapy-resistant, and metastasis-prone states, making this tumor type an archetype of RAX dependence." (PMID 41462674, 2025). "The original tumor cells exhibited diffuse positivity for PRAME and SOX10, while they were focally positive for Melan-A and very focally positive for HMB45, confirming the diagnosis of melanoma." (PMID 40437181, 2025). "In melanoma, ATF2 downregulation upregulates MITF via SOX10, transforming melanoma into a metastatic phenotype." (PMID 40458894, 2025). "Definitive IHC of the resection specimen confirmed melanoma, showing S100 negativity but positivity for HMB45, Melan-A, and SOX10." (PMID 41458594, 2025). "When ATF2 activity is low, SOX10 is highly expressed (phase 1‐ON), leading to high miR‐204 and MITF levels that make melanoma cells show a melanocytic or intermediate phenotype." (PMID 40458894, 2025). "In our network, we searched for three‐node network motifs containing SOX10 and miRNAs and identified a coherent FFL involving SOX10, MITF, and miR‐155 in melanoma." (PMID 40458894, 2025). "Collectively, these results complement the existing models based on the dynamic interplay of known melanoma lineage-defining transcription factors like MITF, SOX10, BRN2, and AXL, by adding KPC1 as a crucial checkpoint." (PMID 41429767, 2025). "Collectively, these observations underscore the pivotal roles of miRNAs and SOX10 in regulating phenotype switching, frequently through pathways involving MITF, emphasizing their intricate interplay in melanoma plasticity." (PMID 40458894, 2025). "Here, the expression of PRAME, SOX10, Melan-A, and HMB45 which are routinely used for melanoma diagnosis were evaluated." (PMID 40437181, 2025). "Immunohistochemical analysis was positive for MART-1, preferentially expressed antigen in melanoma (PRAME), and SOX10." (PMID 40520839, 2025). "The role of DIRC3 in tumour suppression in melanoma is based on the modulation of transcriptional networks governed by MITF and SOX10." (PMID 41463281, 2025). "This methodology facilitates a deeper understanding of the regulation of SOX10 and MITF by miRNAs in melanoma." (PMID 40458894, 2025). "In melanoma, the interaction between UBE2V1 and UBC13 promotes tumor growth via the MEK/FRA1/SOX10 signaling pathway." (PMID 41446875, 2025). "Our network analysis identified feedback and feedforward motifs involving SOX10, MITF, miRNAs, other genes that were (differentially) expressed in melanoma." (PMID 40458894, 2025). "In melanoma, miRNAs collectively target genes like MITF, a transcriptional target of SOX10, to fine‐tune its expression and regulate cell proliferation and migration pathways." (PMID 40458894, 2025).
melanoma (continued). "In our network, the most pertinent hubs are SOX10 and MITF, as both TFs play a crucial role in melanoma." (PMID 40458894, 2025). "Ectopic expression of Myc-DDK-SOX10 (ΔUTR), however, reduces the effect of HK2 depletion, suggesting that the effect observed on colony formation of melanoma cells requires, in part, the SOX10 UTR." (PMID 40956859, 2025). "Histopathology revealed malignant melanoma of acral origin, with immunohistochemical staining positive for MART-1, preferentially expressed antigen in melanoma (PRAME), and SOX10." (PMID 40520839, 2025). "A key diagnostic challenge arises from the complete or partial loss of expression of conventional melanocytic markers, including S100 protein, SRY-Box transcription factor 10 (SOX10), melanoma antigen A (Melan-A), and human melanoma black-45 (HMB-45)." (PMID 40125165, 2025). "We also reviewed the current state of knowledge on the molecular interplay between SOX10, MITF, miRNAs, and other interactors in melanoma." (PMID 40458894, 2025). "SOX10 contributes to melanoma development by regulating the SOX10-MITF pathway, but also contributes to melanoma cell survival, proliferation, and metastasis formation." (PMID 38790661, 2024). "The high frequency of EP300/SOX10 co-amplification identified in human melanomas and previous data from our group demonstrating that EP300 KD leads to decreased SOX10 protein levels strongly suggest a functional relationship between EP300 and SOX10." (PMID 38994683, 2024). "We found that AP-1 factors, particularly c-JUN and JUNB were also induced by WT-Bmal1 or dHLH-Bmal1 in the human WM3629 melanoma cells with corresponding increase in SOX9 and decrease in SOX10 levels." (PMID 38245503, 2024). "In melanoma, FTO knockdown increases m6A methylation of key oncogenes like PD‐1, CXCR4 and SOX10, promoting YTHDF2‐mediated mRNA degradation and making melanoma cells more susceptible to interferon‐γ and anti‐PD‐1 therapy." (PMID 39135292, 2024). "This antagonistic relationship between SOX10 and SOX9 also appears to extend to other cancers, i.e., resulting in melanoma progression upon reduced expression of SOX10." (PMID 39285246, 2024). "Immunohistochemical analysis revealed positive reactions for S-100 protein, antihuman melanoma black-45 (HMB-45) antibody, vimentin (VIM), Sox-10, melan-A, vascular endothelial growth factor, and glial fibrillary acidic protein." (PMID 39495986, 2024). "Of note, SN-MM cell lines were strongly positive for SRY-box transcription factor 10 (SOX10) and preferentially expressed antigen in melanoma (PRAME)." (PMID 38191367, 2024). "Downregulation of SOX10-activated genes by A-485 leads to inhibition of melanoma cell growth as well as downregulated expression of invasion-related genes in MITFlow melanoma cells, including EMT genes that are repressed by SOX10." (PMID 38994683, 2024). "Among the samples, 76.5% (52/68) were positive for S-100, 94.1% (64/68) for HMB-45, 83.6% (56/67) for Melan-A, 100% (29/29) for SOX-10, and 76% (19/25) for PRAME (preferentially expressed antigen in melanoma)." (PMID 39728033, 2024). "Melanoma of the urinary bladder stains positively for S100, HMB45, SOX10, and negatively for keratin and vimentin consistent with our patient’s positively stained immunohistochemistry." (PMID 38933829, 2024). "Malignant melanoma is also a histologically heterogeneous tumor and can be identified by the melanoma markers Melan-A, HMB-45, SOX-10." (PMID 39465766, 2024). "Noticeably, 195 TFs were identified among the SEs predicted target genes, including SOX10 and MITF, master drivers of the melanocytic lineage, and well‐established transcriptional dependency of melanoma." (PMID 37408506, 2023). "In all melanoma cell lines assayed, siRNA-mediated knockdown of CDC20 significantly upregulated SOX10." (PMID 38030698, 2023).
melanoma (continued). "We confirmed that a fraction of CFSE‐labelled patient melanoma cells also expressed varying levels of MITF and/or SOX10 along their migration path, indicating that melanoma ITH was preserved after implantation." (PMID 36692026, 2023). "The melanoma markers MLANA (MART-1), TYR, HMB45 (PMEL), SOX10, S100, and the proliferation marker MIB-1, which recognizes the Ki67 antigen, are used to diagnose primary and metastatic melanoma." (PMID 37762707, 2023). "In all cultured CD90− CD117+ cells, immunostaining confirmed the expression of human melanoma black-45 (HMB-45), SRY-box transcription factor 10 (Sox10), and tyrosinase-related protein 1 (TRP1) (green)." (PMID 37175529, 2023). "In order to evaluate the phenotypic diversity of our samples, we mapped the expression profile of key melanoma cell-state regulatory genes such as the NGFR, RXRG, MITF, SOX10, SOX9 and AXL genes." (PMID 36765773, 2023). "The most frequent markers selected by the respondents included S100, SOX10, HMB45, and Melan-A, which is consistent with previous observations of markers currently used in melanoma diagnosis." (PMID 37760601, 2023). "Uveal melanoma-specific hits were enriched for YREs present in the loci of three master regulators of gene expression in the melanocytic lineage and melanoma: PAX3, SOX10 and MITF." (PMID 37400441, 2023). "This study disclosed a significant co-expression of SOX10, SOX9, and neistin in early primary melanoma." (PMID 38132479, 2023). "Mechanistically, FTO overexpression promoted melanoma development by increasing the key oncogenic genes (PD-1, CXCR4 and SOX10) in mRNA and protein levels and SOX10, and inhibiting IFN-γ-induced melanoma cell death." (PMID 37264402, 2023). "IHC has been able to elucidate many prognostic and predictive biomarkers including MART1/Ki-67, preferentially expressed antigen of melanoma (PRAME), makers of lymphovascular invasion (e.g., CD31/SOX-10) and mismatch repair (MMR) proteins, among many others." (PMID 37900283, 2023). "Altogether, these results demonstrate that SOX10 and DEPDC1B are clinically correlated with SCUBE3 and CD31 expressions in advanced stages of melanoma, consistent with their regulatory relationship in promoting melanoma angiogenesis and metastasis." (PMID 35088579, 2022). "The regulation of a melanocyte-specific factor like SOX10 by SMARCB1 indicates that SMARCB1 likely is essential for survival of the melanocyte lineage and in melanoma." (PMID 35323214, 2022). "S100 protein and other melanoma markers (HMB-45, Melan-A/MART-1, and SOX10) clearly establish a UB melanoma diagnosis." (PMID 35200580, 2022). "Remarkably, inhibition of FTO in melanoma has been found to suppress tumorigenicity and to increase the m6A levels in PD-1, CXCR1, and SOX10, hence enhancing the decay of these m6A-targeted mRNAs by YTHDF2." (PMID 35254013, 2022). "Demethylation of Pdcd-1, Cxcr4, and Sox10 prevented downstream YTHDF2-mediated mRNA decay, resulting in increased expression of these melanoma-promoting genes." (PMID 35350378, 2022). "SOX10 is, like MITF, heterogeneously expressed in melanoma, and has been proposed as a regulator of phenotype switching in cutaneous melanoma since its genetic ablation impairs proliferation and promotes the acquisition of invasive features and drug tolerance." (PMID 35912100, 2022). "In melanoma, inhibition of FTO suppresses tumorigenicity and increases the m6A levels in PD-1, CXCR1, and SOX10, hence enhancing the decay of these m6A-targeted mRNAs by YTHDF2." (PMID 35254013, 2022). "Supporting the in vivo results, the SOX10– IGR-39 melanoma cells showed an increase in migration toward the brain slice, while the SOX10+ MM383 melanoma cells remained confined in their seeding position." (PMID 36040798, 2022).
melanoma (continued). "In contrast, increased SOX10 z-scores were associated with decreased OS of patients with late-stage (n = 192; hazard ratio [HR] = 1.186; 95% confidence interval [CI] = 1.006–1.397; p = 0.03), but not early-stage melanoma (n = 217; HR = 1.203; 95%CI = 1.008–1.436; p = 0.192)." (PMID 35058553, 2022). "All epigenetic drugs had a predominant inhibitory effect on the expression of the melanoma differentiation-related proteins MITF and SOX-10 and of the transcription factor MYC." (PMID 36397155, 2022). "A recent report demonstrated that MITF regulates the expression of SOX10, and our RNAseq data shows that SOX10 is also significantly depleted in the TXNRD1+/− melanoma cells (less than 1% that of the TXNRD1wt cells, padj = 1.2 × 10−10)." (PMID 36291795, 2022). "We co-stained FFPE-embedded primary tumor material preserved for 17 years with two markers, SOX10 and CD146, to map melanoma cells." (PMID 35590073, 2022). "In melanoma cells, where DIRC3 is highly expressed, DIRC3 increases IGFBP5 transcription by preventing the TFs SRY-Box transcription factor 10 (Sox10) and melanocyte inducing transcription factor (MITF) from inhibiting IGFBP5 transcription." (PMID 36093095, 2022). "For example, in melanoma, FTO expression reduces the methylation of SOX10, CXCR4, and PD-1 by m6A in key tumor-promoting melanoma cell-intrinsic genes to promote tumorigenesis." (PMID 36360287, 2022). "We next examined the levels of DDR1 and DDR2 in a collection of melanoma cell lines and short‐term melanoma cultures in relation to the cell state differentiation markers MITF, SOX10, and AXL." (PMID 34957688, 2022). "It has been shown that the expression of melanoma stem cell markers including CD44, NGFR, SOX10, SOX2, and SOX4 was increased by IDTCs." (PMID 36224606, 2022). "We firstly observed the expression pattern of two melanoma markers NKI/beteb and SOX10 in all melanoma FTMs." (PMID 36232952, 2022). "Conclusively, melanoma cells with concurrent MITF and SOX10 promoter methylation are phenotypically different from the MITF-methylated SOX10+ cells." (PMID 36040798, 2022). "Both SOX10 and TBX15 were correlated with the unfavourable prognosis of melanoma patients, and SOX10 positively correlates with SMARCA4." (PMID 36317703, 2022). "In melanoma, FTO promoted resistance to IFN γ-mediated cell death through m6A demethylation of pro-tumorigenic genes Pdcd-1, Cxcr4, and Sox10." (PMID 35350378, 2022). "MITF is known as a central regulator of melanoma cell survival, proliferation, and differentiation, and the factors that regulate it include MC1R, MART-1, SOX10 and PAX3." (PMID 33672928, 2021). "Intriguingly, increased SOX9 expression by PITX1 eventually leads to suppressive effects on cell proliferation and induction of apoptosis via downregulation of SOX10 and SAMMSON, which play an oncogenic role in melanoma." (PMID 34526609, 2021). "As a transcriptional target of SOX10, the expression of SAMMSON is detectable in more than 90% of melanomas." (PMID 34924562, 2021). "In melanoma, FTO promoted the expression of PDCD1, which expresses the PD-1 protein, as well as CXCR4 and SOX10, promoting melanoma tumorigenesis and resistance to immunotherapy." (PMID 33669361, 2021). "Since sox10 is critical to establish neural crest identity, the development of melanocytes, and the maintenance and progression of melanoma, transcriptional regulation of sox10 may be critical for re-establishing or enhancing neural crest identity in melanoma initiation." (PMID 34099848, 2021). "Mass spectrometry analysis of the HIF-2α nuclear interactome in melanoma cells revealed that master proteins involved in melanoma development, such as MITF and SOX10, are HIF-2α binding proteins." (PMID 33964953, 2021). "A pathomorphologist in the final conclusion suggested, taking into account the sarcomatoid melanoma (metastasis) and “MPNST, high-grade”, based on positive sox10 and s100 positive reactions." (PMID 33503841, 2021).